CXCL14 (C-X-C motif chemokine ligand 14)
Diseases named in the same sentence as CXCL14 in open-access papers (continued):
Sharing a sentence is not in itself a finding about the gene and the disease.
tumor (continued). "Although the inflammatory oral microenvironment has been recognized to orchestrate a predominantly pro-tumor immune response, there are also paradoxical effects that can be anticarcinogenic one of which is that of the CXCL14 chemokine." (PMID 35047982, 2020). "Our data indicated that CXCL14 expression in carcinoma cells suppresses tumor growth in vivo by acting in an autocrine or paracrine fashion." (PMID 31014014, 2019). "The role of CXCL14 in cancer is controversial, as it was shown to play either tumor suppressive or tumor supportive roles, depending on the specific tumor type." (PMID 31117166, 2019). "We found that the CXCL14 promoter region in YCU-H891 cells was hypermethylated and that demethylation of the promoter by treatment with 5-aza-2′-deoxycytidine (DAC) restored CXCL14 mRNA expression and in vivo cetuximab-mediated tumor growth suppression." (PMID 31014014, 2019). "There are at least three possible explanations for the apparent discrepancy in the effects of CXCL14 on tumor progression." (PMID 31014014, 2019). "On the other hand, the M2 macrophage phenotype gene, Arg1, and two pro-angiogenesis/tumor genes (Cxcl14 and Mmp13) were identified as poor prognosis markers." (PMID 31507609, 2019). "Although a number of studies have demonstrated a tumor-suppressive role for CXCL14, others showed a pro-tumor one." (PMID 31117166, 2019). "The rate of survival was always significantly higher in transgenic mice than in wild-type mice, indicating that high expression of CXCL14 increased the survival rate and decreased tumor cell metastasis." (PMID 31014014, 2019). "A common feature across all cancers where CXCL14 exerts a tumor-supporting function is its overexpression in the tumor compared to the respective healthy tissue." (PMID 31117166, 2019). "The apparent contradictory or context-dependent effects of CXCL14 on tumor formation have been discussed." (PMID 31014014, 2019). "Through secretion of various cytokines (such as TGF-β, IL-6, CXCL14, etc.)into the tumour microenvironment, CAFs endow cancer cells with proliferative, invasive, and angiogenic properties." (PMID 30911001, 2019). "In this review, we highlight recent studies involving the identification and characterization of CXCL14 in cancer progression and discuss the reasons for the context-dependent effects of CXCL14 on tumor formation." (PMID 31014014, 2019). "Further comparison of CXCL14 expression in the normal and tumor stroma revealed a statistically significant increase in stromal expression of CXCL14 in 15 of 27 (56%) cancer samples; thus, the authors claimed that CXCL14 promoted in vivo growth." (PMID 31014014, 2019). "The chemokine CXCL14 is a known tumor suppressor involved in antimicrobial immunity and inflammatory processes." (PMID 31660891, 2019). "These chemokines, as well as CXCL4, CXCL4L1, and CXCL14, have been reported to inhibit angiogenesis, dampening tumor growth and metastasis." (PMID 30591657, 2018). "Consistently, our results here show that CXCL14 reexpression in HPV-positive cells significantly suppresses tumor growth in vivo." (PMID 27143385, 2016). "Because tumor growth is only partially suppressed by Cxcl14 reexpression in Rag1−/− mice, our results indicate that both innate and adaptive immune responses play important roles in the antitumor functions of CXCL14." (PMID 27143385, 2016). "Strikingly, Cxcl14 reexpression in MOE/E6E7 cells significantly suppressed tumor growth in wild-type C57BL/6 mice, while vector-transduced MOE/E6E7 cells rapidly formed tumors." (PMID 27143385, 2016). "Mice with Cxcl14 reexpression show dramatically increased natural killer and T cells in the tumor-draining lymph nodes." (PMID 27143385, 2016). "This is consistent with our tumor growth results showing a moderate delay in tumor growth by Cxcl14 reexpression in Rag1−/− mice, in which NK cell infiltration is increased in the absence of T cells (data not shown)." (PMID 27143385, 2016).
tumor (continued). "The strongly induced chemokine CXCL14 is known to exert both tumor-suppressive and tumor-promoting effects in mammals." (PMID 28003019, 2016). "We demonstrated that DAC increased the expression of CXCL14 messenger RNA (mRNA) and enhanced the tumour-suppressive effect of cetuximab." (PMID 27399917, 2016). "CXCL14 is a chemokine that has been shown to be upregulated in tumor myoepithelial cells and enhances the proliferation, migration, and invasion of epithelial cells after binding to their receptors." (PMID 26892682, 2016). "We also observed that the CXCL14 promoter region in YCU-H891 cells was hypermethylated, and that demethylation of the promoter by treatment with 5-aza-2′-deoxycytidine restored CXCL14 mRNA expression and in vivo cetuximab-mediated tumour growth suppression." (PMID 27399917, 2016). "CXCL14, on the other hand, can function in the microenvironment, resulting in similar levels of tumour suppression when forced to be expressed in the cells, without any observable side effects." (PMID 25765541, 2015). "In turn, expression of CXCL14 chemokine with enigmatic physiological function is connected with the tendency of tumor infiltration described on the basis of in vitro studies." (PMID 26497896, 2015). "In this analysis, half of the Wt and CXCL14 Tg mice were injected (i.p.) with anti-asialo-GM1 antibody in order to investigate the participation of NK cells in the suppression of tumour cell metastasis." (PMID 25765541, 2015). "There are several possible explanations for the apparent discrepancy in the effects of CXCL14 on tumour progression, e.g., cell type-specific functions and/or stage-specific effects of CXCL14 during tumour progression." (PMID 25765541, 2015). "In the tumor of shS100A6-injection group, the expression of CXCL14 in the tumor tissue was obviously stronger than in the tumor tissue of shControl-injection group." (PMID 25760073, 2015). "CAF-derived chemokines CXCL-12 or CXCL-14 recruit bone marrow-derived cells, macrophages, and other immune cells into the tumor microenvironment, enabling tumor growth." (PMID 25853091, 2015). "Tumour cell chemiluminescence was lower in the CXCL14 Tg mice than in the Wt animals, and the intensity of this chemiluminescence was increased in both Wt and Tg mice following injection of anti-NK1.1." (PMID 25765541, 2015). "For example, the chemokine CXCL14 is expressed by cancer cells and CAFs of different tumor types, and CXCL14 acting through fibroblasts exerts tumor-promoting effects in vivo by stimulating angiogenesis and macrophage infiltration." (PMID 24734219, 2014). "CAFs produce CCL2, CCL5, CCL7, CXCL8, and CXCL14 and these chemokines promote tumor progression mainly by enhancing the motility of tumor cells." (PMID 24966464, 2014). "CXCL14 is a pro-migratory chemokine and plays an important role in tumor recognition by the immune system." (PMID 24833255, 2014). "We next analyzed the relevance between CXCL14 expression in tumor tissues and clinicopathologic factors." (PMID 23294544, 2013). "CXCL14 is therefore a useful prognostic factor for predicting the outcome of patients with CRC who have had a surgical resection of their tumor." (PMID 23294544, 2013). "Patients with stage III CRC were divided into low-CXCL14-expressing tumor group (n = 66) and high-CXCL14-expressing tumor group (n = 61)." (PMID 23294544, 2013). "A group of 4 genes (ARX, GPR17, LHX2 and CXCL14) well stratified LGGs between infratentorial and supratentorial tumours." (PMID 23947815, 2013). "Strong CXCL14 staining was mainly observed in the cytoplasm of tumor cells, while partially in the normal mucosa." (PMID 23294544, 2013). "Elevated CXCL14 expression in tumor specimens (n = 135) from stage III/IV patients correlated with worse overall survival (risk ratio, 3.087; 95% CI, 1.866-5.107; P < 0.001)." (PMID 23294544, 2013).
tumor (continued). "One of the challenges to effective therapy lies in understanding the mechanisms through which the chemokine CXCL14 promotes cell transformation and tumor progression." (PMID 23294544, 2013). "Tumoral CXCL14 expression levels were significantly correlated with TNM (Tumor-node-metastasis) stage, histodifferentiation, and tumor size." (PMID 23294544, 2013). "Understanding the mechanisms through which the chemokine CXCL14 promotes cell transformation and tumor progression is key to effective therapy." (PMID 23294544, 2013). "The mechanisms through which CXCL14 promotes or inhibits tumor progression need to be further analyzed." (PMID 23294544, 2013). "By univariate analysis, CXCL14 expression, number of lymph nodes, and tumor size were significantly correlated with disease recurrence." (PMID 23294544, 2013). "Results obtained from the present study together with others indicate a need for further analysis of possible tumor type- and stage-specific effects of CXCL14 in other tumors." (PMID 23294544, 2013). "The data also indicate that CXCL14/BRAK, which was first found as tumor progression suppressor in vivo for HNSCC cells, also suppresses tumors derived from other tissues." (PMID 23762619, 2012). "Our data indicate that expression of CXCL14/BRAK in tumor cells suppresses tumor growth in vivo by acting in an autocrine or paracrine fashion." (PMID 23762619, 2012). "Furthermore, CXCL14's influence on tumor progression was confirmed in a spleen-to-liver metastasis model, where its overexpression reduced metastatic spread." (PMID 42193871, 2026). "For instance, CXCL14 may suppress tumor growth, while S100A11 promotes cancer cell survival and migration." (PMID 41182757, 2025). "Notably, CXCL14 demonstrated superior predictive performance compared to commonly used clinical tumour markers by ROC curves, highlighting its substantial predictive importance." (PMID 40162549, 2025). "Additionally, Cxcl14 was found to promote tumour growth and contribute to resistance against osimertinib." (PMID 40162549, 2025). "Furthermore, using a mouse metastasis model induced by tail vein injection of cancer cells described before, CM derived from Cxcl14‐OE fibroblasts promoted LUAD tumour metastasis, with decreased survival." (PMID 40162549, 2025). "Overall, these findings indicated that transitional CXCL14+ myCAFs could enhance the EMT in tumour cells and promote the angiogenesis of vascular endothelial cells." (PMID 40162549, 2025). "Furthermore, metastatic OSCCs express less CXCL14 than the primary tumors, supporting the notion that CXCL14 are implicated in TIL recruitment and tumor suppression." (PMID 40724900, 2025). "Moreover, the combination of CXCL14 knockdown in CAFs with ERCC4 knockdown in T24 cells resulted in the most substantial tumor growth inhibition." (PMID 40898244, 2025). "Similarly, CXCL14, highly expressed in CAFs, recruits immune and stromal cells to support tumor growth." (PMID 39950116, 2025). "The clinical relevance of these biomarkers has been extensively validated: CXCL14 expression in tumor stroma has been confirmed as an independent survival marker, with fibroblast-derived CXCL14 promoting epithelial-to-mesenchymal transition and metastasis through ACKR2-dependent mechanisms." (PMID 41139924, 2025). "Both oncogenic and tumor-suppressive functions of CXCL14 have been reported among various cancers." (PMID 39358777, 2024). "Mechanistically, anlotinib suppresses the expression of TFRC by inhibiting the VEGFR2‐AKT‐HIF axis, which in turn enhances the secretion of CXCL14 and recruits tumour‐infiltrating CD8+ T cells, particularly PD‐1+CD8+ T cells, thereby potentiating the anti‐tumour efficacy of anti‐PD‐1 treatment." (PMID 39095323, 2024).
tumor (continued). "With the completion of adenoviral production, the full cassette combining CXCL14 and E6/ E7 epitopes, CXCL14 alone, or E6/E7 epitopes alone, will be evaluated for their effect on in vivo tumor growth and T cell infiltration by intratumoral injection into tumor-bearing immunocompetent syngeneic mice." (PMID 38911052, 2024). "High levels of CXCL14 expression are correlated with overall patient survival in colorectal, breast, endometrial, intraepithelial, and head and neck cancers and suppress tumor progression." (PMID 38400076, 2024). "Interestingly, CXCL14 is considered critical to the upregulation of the major histocompatibility complex (MHC) class I expression in tumor cells." (PMID 38519456, 2024). "Obtained results suggest the usefulness of CXCL5 and CXCL16 in the determination of distant metastases and differentiation between TNM (Tumor-Node-Metastasis) stages, as well as the usefulness of CXCL14 and CRP combination in CRC detection (primary or recurrence)." (PMID 37848726, 2023). "CHI3L1, COL1A1, and CXCL14 have been shown to be related to tumor metastasis and invasion." (PMID 37480002, 2023). "CXCL14 from epithelial cells, conversely inhibits tumor development." (PMID 37393391, 2023). "In addition, the forced expression of CXCL14, another chemokine recognized as an important tumor suppressor gene that is epigenetically silenced during lung carcinogenesis, led to dramatic tumor growth reduction." (PMID 37046597, 2023). "CXCL14 plays tumor-supportive or suppressive roles due to the differences in cell derivation." (PMID 36721112, 2023). "Mostly, CXCL14 produced by epithelial cells has been shown to overwhelm the tumor cells growth." (PMID 37848726, 2023). "The expression of Groα and CXCL14 had higher expression in the HNSCC tumor." (PMID 37151389, 2023). "Hence, the clinical meaning of the downregulation of CXCL14 and reduced fraction of dendritic cells after CaEP awaits further elucidation, even though current scientific knowledge links such changes in the tumor microenvironment with unfavorable outcomes." (PMID 37688629, 2023). "CXCL14 derived from different cells affects tumor progression in different ways." (PMID 37393391, 2023). "We next explored the correlation between CXCL14 and different cells in the tumor microenvironment." (PMID 37563546, 2023). "High levels of CXCL14 reduce tumor growth and metastasis (blue arrows)." (PMID 36012586, 2022). "It is not clear whether these cells or subsets of these cells might have any anti-tumor function in the tumor suppressive roles of CXCL14." (PMID 36012586, 2022). "Nevertheless, it is of great interest to investigate whether CXCL14 can act as an antagonist to the well-established CXCL1/5/8-CXCR2 signaling in the tumor microenvironment." (PMID 36012586, 2022). "Therefore, we assumed that increased CXCL14 secretion by fibroblasts in the microenvironment promoted tumor metastasis, resulting in poor prognosis." (PMID 35769715, 2022). "The results showed that CXCL14 knockdown significantly inhibited tumor growth in xenografts mice." (PMID 35669852, 2022). "There have been specific studies about CXCL12 and CXCL14 in CAFs in tumor progression." (PMID 36119108, 2022). "A PC xenograft mouse model was used to assess the role of CXCL14 in tumor growth in vivo." (PMID 35669852, 2022). "Using IHC, CXCL14 expression was evaluated in both tumor and stromal tissues." (PMID 35769715, 2022). "Moreover, the expressions of CXCL14, CCL20, CCL24, and CCL26 were associated with tumor purity and infiltration of CD4+ T cell, CD8+ T cell, B cell, macrophage, dendritic cell, and neutrophil in PCa." (PMID 36275733, 2022). "Prostate cells expressing CXCL14 resulted in tumor growth inhibition." (PMID 36012586, 2022). "The effect of CXCL14 on tumor growth depends on the cell type expressing the factor." (PMID 35769715, 2022). "Conversely, other data have shown that CXCL14 promotes BC tumor growth, invasion, and metastasis." (PMID 35725915, 2022).
tumor (continued). "On the other hand, low levels of CXCL14 enhance tumor growth and metastasis (red arrows)." (PMID 36012586, 2022). "Additionally, CXCL14 transgenic mice showed a suppressed rate of carcinogenesis and decreases in tumor volume and lung metastasis." (PMID 36012586, 2022). "Similarly, the NG2– cell population, including tumor cells, produced negligible levels of Cxcl14 in both FGF-2+ and FGF-2– tumors." (PMID 35439170, 2022). "Overexpression of CXCL14 attenuated xenograft tumor growth and lung metastasis of MDA-MB-231 cells." (PMID 36012586, 2022). "We then used IF to detect the NK cell infiltration in tumours, which demonstrated that the number of infiltrating CD45+ cells in the tumour‐bearing mice was remarkably elevated in response to CXCL14 overexpression, but was decreased in response to CXCL14 knockdown." (PMID 33733587, 2021). "Whether the contradictory functions of CXCL14 in tumor progression are due to the types of tumors awaits further investigation." (PMID 34744744, 2021). "At three weeks after injection, the expression of CXCL14 mRNA in tumours was determined by RT‐qPCR, which showed that CXCL14 expression was significantly up‐regulated in the tumour‐bearing mice injected with oe‐mCXCL14, but notably down‐regulated in those injected with sh‐mCXCL14." (PMID 33733587, 2021). "The conflicting biological functions of CXCL14 in tumor biology have been addressed." (PMID 34744744, 2021). "For instance, CXCL14 promoted GBM progression by modulating tumor cell proliferation and migration." (PMID 34603309, 2021). "The mRNA levels of CXCL14 were higher in OC specimens than in non-tumor ovarian tissues." (PMID 34789307, 2021). "CXCL14 plays a double-sided role in the regulation of tumor development." (PMID 34744744, 2021). "In the epigenetic regulation, E7 could upregulate DNA methyltransferases DNMT1, DNMT3A, and DNMT3B to promote genomic instability 17, induce methylation of CXCL14 to promote tumor growth via angiogenesis." (PMID 34729114, 2021). "In the CXCL14 transgenic mice, all cells could highly express CXCL14, which might affect the anti-tumor or pro-tumor effect of CXCL14 from two aspects." (PMID 34744744, 2021). "However, a previous study showed that ROS stimulated angiogenesis and tumor progression by reducing the expression of CXCL14 via EGFR/MEK/ERK signaling pathway in HNSCC cells." (PMID 34744744, 2021). "Similarly, CXCL14 expression was significantly higher in OC (84%, 42 in 50 cases) relative to non-tumor ovarian tissues, which was demonstrated using immunohistochemical staining." (PMID 34789307, 2021). "In addition, it was also found that the tumour volume and weight of mice were considerably decreased upon CXCL14 overexpression, but remarkably increased after CXCL14 knockdown." (PMID 33733587, 2021). "Similarly, in BC, a subset of myofibroblastic CAFs (CAF-S1: CD-29Med FAPHi FSP-1Low−Hi αSMAHi PDGFRbMed−Hi CAV-1Low) secreting differentially higher amount of CCL-11, CXCL-12, CXCL-13, and CXCL-14 was predominantly detected close to epithelial tumor cells." (PMID 33553157, 2020). "This CXCL14 involvement in PD may be considered as one of the methods by which anti-tumor responses are supported." (PMID 35047982, 2020). "CXCL14 also stimulated ACKR2 to mediate tumor invasion and metastasis." (PMID 32708730, 2020). "The third possibility is that CXCL14 may also stimulate multiple signals and induce contrasting effects such as tumor suppression or tumor progression." (PMID 31014014, 2019). "Further studies are needed to clarify the specific molecular mechanisms and/or effect of levels of CXCL14 on tumor suppression and regulation of CXCL14 gene expression in order to facilitate the application of CXCL14 as a molecular target in cancer therapy and prevention." (PMID 31014014, 2019). "However, some studies have reported that over-expression of CXCL14, especially in stromal cells, stimulated the progression of tumor formation." (PMID 31014014, 2019).